AFP (alpha fetoprotein)
Diseases named in the same sentence as AFP in open-access papers (continued):
Sharing a sentence is not in itself a finding about the gene and the disease.
liver disease (continued). "In the present paper, we report a case of non-cirrhotic portal hypertension in patient with inactive HBV carrier status and persistently increased levels of AFP." (PMID 18842148, 2008). "In particular, in AFP-negative HCC cases, DKK1 may be more effective in differentiating HCC from nonmalignant liver diseases." (PMID 40922300, 2025). "Indeed, AFP is not elevated in pure seminomas; LDH serum levels can be elevated in other conditions, such as liver disease or tissue damage, and hCG can be elevated in both seminomas and non-seminomas, reducing its ability to differentiate between tumor types." (PMID 40723290, 2025). "Also, this group of patients has shown significantly higher levels of AFP in the absence of HCC, compared to other liver disease groups, which is all in accordance with the published data." (PMID 37569857, 2023). "Elevated serum AFP-levels > 10 ng/mL (>20 ng/mL) in non-HCC patients were documented most frequently in HCV patients with 11.5% (5.0%) and in HBV patients with 8.5% (4.6%), compared to the cohort with liver diseases of other etiology with 7.4% (1.9%)." (PMID 34451832, 2021). "In the last two cases in which the algorithm detected ‘high risk’ HCC behaviour during screening prior to HCC development, the AFP did not change clinical management and the HCC was detected incidentally by cross sectional imaging performed for decompensated liver disease (jaundice and ascites)." (PMID 27308823, 2016). "However, serum prothrombin induced by the absence of vitamin K or antagonist-II (PIVKA-II) measurement not only more specifically differentiates HCC from other hepatic diseases, but PIVKA-II levels are not also usually correlated with those of AFP." (PMID 24455683, 2013).
Hepatitis (244 papers, 1997 to 2026). Inflammation of the liver. "Future cases would be strengthened by the routine inclusion of AFP and hepatitis serology in the diagnostic workup for cancer‐associated stroke." (PMID 41487984, 2026). "HCC is often associated with a history of hepatitis, elevated AFP, and unique imaging characteristics." (PMID 39411128, 2024). "The previously ambiguous improvement in survival due to AFP testing appears to be attributed to the enhanced effectiveness of antiviral therapy, which, when properly controlling underlying hepatitis, amplifies the diagnostic performance of AFP." (PMID 38201578, 2023). "84.9% patients were male (28/33), ECOG PS of 0–1 score (27/33, 81.8%), Child‐Pugh class A (25/33, 75.8%), AFP level ≥400 ng/ml (22/33, 66.7%) and associated with hepatitis at baseline." (PMID 35633045, 2023). "ATIC expression was markedly associated with serum AFP level (p = 0.0011), hepatitis status (p = 0.0352), vascular invasion (p = 0.0384), histologic grade (p = 0.0006) and Tumor node metastasis (TNM) stage (p = 0.0086) in HCC patients." (PMID 29246230, 2017). "To avoid the influence of non-tumour-originating AFP fluctuations (ie, those associated with hepatitis activity), we only assessed AFP response in patients with baseline AFP levels above 200 ng ml−1 and received treatments for at least 8 weeks." (PMID 20808309, 2010). "In addition to the type of treatment, our study identified the presence of hepatitis and serum AFP level at recurrence as independent factors associated with PRS in the multivariate analysis." (PMID 32108433, 2020). "They found that early tumor recurrence was mostly associated with tumor-related factors, including microvascular invasion, multiple tumors, and elevation of serum AFP level, while late tumor recurrence was most associated with host-related factors, including liver fibrosis and hepatitis activity." (PMID 30606203, 2019). "Further, none of these studies had patients stratified pretreatment for relevant predictors of HCC risk, like age, hepatitis severity, alpha-fetoprotein (AFP) levels and co-morbidities, therefore making a comparison of the outcomes between treated and untreated patients difficult." (PMID 26295392, 2015). "Moreover, mildly elevated serum AFP levels may be associated with hepatitis, pregnancy, and reproductive tumors and should be carefully considered." (PMID 37519810, 2023). "The analysis results revealed that the mRNA expression level of STARD4 was significantly correlated with tumor size (P = 0.032), alpha-fetoprotein levels (P = 0.032), hepatitis (P = 0.005), TNM stage (P < 0.001), and microvascular infiltration (P < 0.001)." (PMID 40831538, 2025). "As a result, a total of 11 key variables including Age, Hepatitis, AFP, CA199, CEA, ALT, AST, APHE, Washout, Kupffer, and Emean were left for the LASSO regression." (PMID 39402127, 2024). "Multivariable Cox regression analysis was performed, including group, age, hepatitis, AFP, ALB, TB, ALBI grade, ascites, maximum tumor size, tumor number, BCLC stage, and Child-Pugh grade." (PMID 38380330, 2024). "The 15 newly added hepatitis patients were active hepatitis patients with elevated AFP expression, and we found that serum IL-41 expression significantly varied among hepatitis patients." (PMID 38835390, 2024). "While its expression is repressed after birth by epigenetic mechanisms, it is known that the adult liver reactivates the AFP locus and secretes the protein in response to fibrosis, hepatitis, and several hepatic cancers." (PMID 36301669, 2023). "(HR: 0.66, 95% CI: 0.59, 0.73, P:0.001) The 5-year survival rate is significantly related to tumor size, AFP level, the number of involved lymph nodes, differentiation grade, tumor size, hepatitis, blood group type, and metastasis were related." (PMID 37875876, 2023).
Hepatitis (continued). "The serum level of AFP correlated closely with tumor differentiation and aggressiveness, and was also a suggested indicator of hepatitis activity and severity, predicting the prognosis of HCC patients." (PMID 36936655, 2023). "The results of the other subgroups of patients with different clinico-pathological characteristics were also statistically significant, with the exception of the parameter of hepatitis (P=0.11) and AFP greater than or equal to 400 ng/ml (P=0.05)." (PMID 37598406, 2023). "At the moment, AFP is the most important clinical diagnostic measure for HCC; however, recent research has shown that AFP expression can also increase in other liver illnesses, such as hepatitis; as a result, its specificity is quite poor." (PMID 36059812, 2022). "This proves that the IRGs signature combines clinical characteristics such as AFP levels and hepatitis to further enhance clinical value and predictive power." (PMID 35397536, 2022). "It was used as a biosensor for AFP with a detection limit of 1.18 ng mL−1 and a quantification limit of 3.58 ng mL−1 on serum samples obtained from healthy and hepatitis patients." (PMID 35055294, 2022). "Compared with the control hOF-iPSCs, the hOF-iPSCs cultured on the normal livers and the livers with hepatitis significantly expressed AFP and AAT." (PMID 34831050, 2021). "Our results showed that the combination of AFU and AFP protein biomarkers detected NBNC-HCC in the normal population and in hepatitis-related HCC in the at-risk population with stable and reliable cut-off values." (PMID 33628599, 2021). "The AFP/AFU panel had a high degree of accuracy for differentiating NBNC-HCC from healthy controls and hepatitis-related HCC in patients at risk for developing HCC." (PMID 33628599, 2021). "Noting that common neonatal conditions (e.g., prematurity, jaundice and hepatitis) trigger elevated AFP, it seems plausible that our MH subjects deviated from this normal baseline – in which case, MH-onset age would be underestimated." (PMID 32595522, 2020). "To highlight the significance of ANRI, we built model 1 including gender, hepatitis, AFP, and CA199." (PMID 31903730, 2020). "In our study, we found that sex, hepatitis, AFP, CA199, and ANRI were the independent differential factors between ICC and HCC through the multivariable logistic regression analysis." (PMID 31903730, 2020). "In conclusion, we demonstrated that sex, hepatitis, AFP, CA199, and ANRI are the independent differential factors between ICC and HCC." (PMID 31903730, 2020). "Age, sex, hepatitis B positive rate, tumor size, alpha-fetoprotein (AFP) positive rate, abnormal prothrombin positive rate, and Child-Pugh grade were involved." (PMID 32508913, 2020). "To highlight the significance of ANRI, we established model 2 which consists of sex, hepatitis, AFP, and CA199." (PMID 31903730, 2020). "Our statistical analysis showed that high expression of FOS was associated with Hepatitis B Virus (HBV) infection background, alpha-fetoprotein (AFP) level, and macrovascular invasion." (PMID 32280695, 2020). "Hepatitis, AFP, and ANRI were negatively related to ICC, while female and CA199 were positive factors in this ICC differential nomogram." (PMID 31903730, 2020). "Many risk factors are reported to influence postoperative recurrence of HCC, such as tumor size, tumor number, staging, vascular invasion, pathologic differentiation, serum AFP level, liver function reserve, and hepatitis viral status." (PMID 31673081, 2019). "Alpha-fetoprotein (AFP) and hepatitis history were found to be significantly correlated with the expression of PD-L1 (P = 0.04 and P = 0.04, respectively)." (PMID 30718977, 2019). "The expression of PD-L1 was found to be significantly correlated with alpha-fetoprotein, hepatitis history, and tumour-infiltrating lymphocytes." (PMID 30718977, 2019).
Hepatitis (continued). "On the other hand, AFP levels decrease according to decreased hepatitis activity by nucleos(t)ide analogs in chronic hepatitis B and by interferon-based treatments in chronic hepatitis C." (PMID 28620797, 2017). "The first uses host, surgical, and pathological factors such as serum alpha fetoprotein (AFP), hepatitis activity, tumor diameter, tumor number, and vascular invasion to predict surgical prognosis." (PMID 27027439, 2016). "Hepatitis, liver cirrhosis, portal vein thrombosis, and increased serum AFP levels are uncommon in PHNET patients." (PMID 26272674, 2015). "Hepatitis B viral aetiology was shown in this study to be significantly associated with high DCP and AFP values." (PMID 26341083, 2015). "The majority of HCC patients has a history of hepatitis, liver cirrhosis, and increased serum levels of alpha-feto protein (AFP)." (PMID 26272674, 2015). "Bilirubin is a break-down product of heme whose biliary excretion is counteracted by intrahepatically produced IL-1 and IL-6 in sepsis, while alpha-fetoprotein is produced in the regenerating liver following hepatitis or intoxication." (PMID 24642872, 2014). "Downregulation of AFP resulted from steroid and liver protection therapy for hepatitis instead of surgery." (PMID 24059753, 2013). "In patients with inflammatory conditions such as hepatitis, the value of AFP is limited as AFP levels can be elevated beyond the threshold in the absence of measureable cancer and negative in cases of obvious malignancy." (PMID 24957758, 2012). "We identified 7 proteins that significantly differentiate HCC patients from hepatitis patients (p < 0.05) (AFP, CTNNB, CSF1, SELL, IGFBP6, IL6R, and VCAM1)." (PMID 19578489, 2008). "Proteins that uniquely distinguish HCC patients with low AFP from patients with hepatitis include IL1RN, IFNG, CDKN1A, RETN, CXCL14, and FGF2." (PMID 19578489, 2008). "CTNNB and SELL appear to have the potential to distinguish not only HCC patients from hepatitis patients, but also HCC patients with AFP < 20 ng/ml from hepatitis patients." (PMID 19578489, 2008). "Serum DCP in HCC patients positively correlated with gender, tumor size, tumor number, vascular invasion, hepatitis, AFP, ALT, AST, total bilirubin, direct bilirubin, indirect bilirubin, albumin, and A/G ratio (p < 0.05), but negatively correlated with age (p < 0.05)." (PMID 40230049, 2025). "Mechanistically, this phenomenon may be associated with inflammatory reactions, considering that benign inflammatory diseases—e.g., colitis and hepatitis—can also present with elevated AFP and DCP." (PMID 40534866, 2025). "It is due to the fact that AFP levels fluctuate during hepatitis flares." (PMID 36873737, 2023). "For example, the accuracy of AFP in patients with hepatitis may be lower than in patients with other aetiologies, as hepatitis infection can affect AFP levels." (PMID 39139275, 2023). "Of these 11 patients, 9 had documented hepatitis exacerbations when the baseline AFP was assayed." (PMID 36233438, 2022). "Also, des-gamma-carboxyprothrombin (DCP) is a more specific biomarker in HCC compared to AFP as it is elevated in HCC, which can be elevated in several conditions that cause active hepatitis." (PMID 35547447, 2022). "The AFP/AFU combination could be used to identify NBNC-HCC from healthy controls and hepatitis-related HCC from at-risk patients." (PMID 33628599, 2021). "In addition to the two biomarkers (ALT and AFP) attributed to hepatitis flares, IL-17 represents a distinct immunological aspect of the disease." (PMID 33865328, 2021). "Comparing model 1 including gender, hepatitis, AFP, and CA199 (C index = 0.903, 95% CI: 0.849‐0.957) and model 2 enrolling AFP and CA199 (C index = 0.850, 95% CI: 0.791‐0.908), the nomogram showed a better discrimination between ICC and HCC, with a C index of 0.920 (95% CI, 0.872‐0.968)." (PMID 31903730, 2020). "The expression of PD-L1 was significantly correlated with AFP, hepatitis history, and TIL." (PMID 30718977, 2019).
Hepatitis (continued). "The expression of PD-L1 was significantly correlated with AFP, hepatitis history, and TILs." (PMID 30718977, 2019). "However, the specificity of AFP is poor and AFP can also increase in severe hepatitis, ovarian tumors, and embryonal tumors." (PMID 28321390, 2017). "Hepatitis activity may elevate AFP levels in CHB, and elevated AFP levels may just signify increased risk for future development of HCC." (PMID 29290966, 2017). "Similar to chronic hepatitis C virus infection, hepatitis activity and fibrosis stage may influence AFP levels in CHB." (PMID 27997559, 2016). "Serum AFP level may be high in patients with drug or alcohol abuse or with chronic liver disease such as hepatitis or cirrhosis, but in these cases, the level is usually <100 ng/mL." (PMID 24993566, 2014). "However, because of small sample numbers, the comparison of CTNNB levels between HCC patients with AFP < 20 ng/ml and hepatitis patients (n = 6) only approaches significance (p = 0.07) (data not shown)." (PMID 19578489, 2008). "Importantly, we also identified 8 proteins that significantly differentiate HCC patients with ‘normal’ levels of AFP (< 20 ng/ml) from hepatitis patients (p < 0.05) (IL1RN, IFNG, CDKN1A, RETN, CXCL14, CTNNB, FGF2, and SELL)." (PMID 19578489, 2008). "Seven of 13 samples from hepatitis patients also showed positive AFP mRNA expression." (PMID 9062418, 1997). "Because we analyzed all of the serial screening data rather than baseline or final ones, AFP values associated with hepatitis flare may not have significantly affected the performance of the nomogram." (PMID 29290966, 2017). "Serum levels of AFP and PIVKA-II were greatly elevated in HCC patients compared to those with LC and hepatitis (both p < 0.05)." (PMID 40241895, 2025). "Alpha-fetoprotein (AFP), carbohydrate antigen 19-9 (CA19-9), and hepatitis serologies were all within normal limits." (PMID 41492618, 2025). "The AUC was 0.777 when AFP, HOTAIR, and 1/HBeAg were combined to distinguish HCC from LC and the hepatitis group." (PMID 39128100, 2024). "We found that the combination of AFP, HOTAIR, and the reciprocal index of HBeAg (1/HBeAg) had a high AUC of 0.829 when distinguishing HCC from the hepatitis group." (PMID 39128100, 2024). "A significant benefit in OS was observed for HAIC+T+P in the following subgroups: hepatitis, Child–Pugh B, BCLC stage B, tumor number > 3, and AFP > 400 ng/ml." (PMID 37207144, 2023). "Based on subgroup analyses of hepatitis, Child–Pugh B, BCLC stage B, tumor number > 3, and AFP > 400 ng/ml, HAIC+T+P contributed to a better OS, whereas the other subgroups did not." (PMID 37207144, 2023). "The laboratory tests consisted of alpha-fetoprotein (AFP), blood tests (i.e., total bilirubin, alanine transaminase, aspartate aminotransferase, and alkaline phosphatase), and hepatitis tests (i.e., HBsAg, HBsAb, HBeAg, HBeAb, HBcAb, and HCVAb)." (PMID 35885198, 2022). "This study explored the clinical value of three markers of AFP, AFP-L3 and CTCs in the diagnosis of HCC, liver cirrhosis, and hepatitis, when used alone or in combination." (PMID 33971914, 2021). "Overall, the AFP/AFU panel improved the accuracy for diagnosing all-stage and early-stage hepatitis-related HCC compared to any other single marker." (PMID 33628599, 2021). "For all-stage hepatitis-related HCC vs. CH and LC, the ROC curves showed that the AFP/AFU combination had an AUC of 0.835 (95% CI: 0.784–0.877), a sensitivity of 69.1%, and a specificity of 87.4%." (PMID 33628599, 2021). "The percentages of AFP- and AAT-positive hOF-iPSCs in the normal and hepatitis liver groups were significantly higher than those in the control cells." (PMID 34831050, 2021). "Of note, stages of hepatitis activity (G) were positively correlated with DIF, AST, ALT, AFP, and TB (p < 0.05)." (PMID 33860040, 2021). "There was a statistically significant decrease in all evaluated biochemical markers of hepatitis (ALT, AST, GGT) and AFP (p < 0.0001)." (PMID 33652777, 2021).